TAS2R43 (taste 2 receptor member 43)
Description:
Gustducin-coupled receptor immplicated in the perception of bitter compounds in the oral cavity and the gastrointestinal tract. Signals through PLCB2 and the calcium-regulated cation channel TRPM5. Activated by the sulfonyl amide sweeteners saccharin and acesulfame K. In airway epithelial cells, binding of bitter compounds increases the intracellular calcium ion concentration and stimulates ciliary beat frequency. May act as chemosensory receptors in airway epithelial cells to detect and eliminate potential noxious agents from the airways (By similarity).
Synonyms: T2R43; T2R52
Tractability: Antibody: its Gene Ontology location is reachable by antibodies, with high confidence; UniProt predicts a signal peptide or a membrane-spanning region. PROTAC: a small molecule that binds it is known.
Target class: Membrane receptor; Taste receptor (taste family GPCR); Taste family G protein-coupled receptor
Gene: Protein-coding gene on chromosome 12 (11,091,287 to 11,092,313, reverse strand). Ensembl gene ENSG00000255374.
Subcellular location: Membrane; Cell projection, cilium membrane
Pathways (Reactome):
Signal Transduction: Class C/3 (Metabotropic glutamate/pheromone receptors); G alpha (i) signalling events
Sensory Perception: Sensory perception of sweet, bitter, and umami (glutamate) taste
Gene Ontology:
Molecular function: bitter taste receptor activity; taste receptor activity; G protein-coupled receptor activity
Biological process: detection of chemical stimulus involved in sensory perception of bitter taste; G protein-coupled receptor signaling pathway; sensory perception of taste
Cellular component: motile cilium; membrane; plasma membrane; ciliary membrane
Genetic constraint (gnomAD): Loss-of-function variants: 0 observed, 0.21 expected, observed/expected ratio (o/e) 0, 90% interval 0 to 1.88. That is too few expected variants to judge how well the gene tolerates losing a copy. Missense variants: 246 observed, 194.68 expected, observed/expected ratio (o/e) 1.26, 90% interval 1.14 to 1.4. Synonymous variants: 76 observed, 64.83 expected, observed/expected ratio (o/e) 1.17, 90% interval 0.97 to 1.42.
Homologues: Orthologues: chimpanzee TAS2R43 (99% identical), dog CAFA-T2R43 (60% identical), mouse Tas2r120 (48% identical), rat Tas2r120 (46% identical), rat Tas2r136 (45% identical), mouse Tas2r136 (43% identical). Paralogues in human: TAS2R31 (89% identical), TAS2R46 (88% identical), TAS2R30 (81% identical), TAS2R20 (67% identical), TAS2R50 (66% identical), TAS2R19 (64% identical), TAS2R14 (45% identical), TAS2R13 (43% identical), TAS2R7 (38% identical), TAS2R9 (36% identical), TAS2R10 (35% identical), TAS2R3 (34% identical), and 11 more.
Diseases named in the same sentence as TAS2R43 in open-access papers:
TAS2R43 is named in the same sentence as 11 diseases in open-access papers, as found by Europe PMC text mining. Sharing a sentence is not in itself a finding about the gene and the disease. The quoted sentences say what the papers report.
breast carcinoma (2 papers, 2022 to 2025). "The TAS2Rs with highest expression in HNSCC (TAS2R4, TAS2R14, TAS2R19, TAS2R20, TAS2R30, TAS2R43, and TAS2R45) overlap with TAS2Rs expressed at increased levels in breast cancer." (PMID 34717036, 2022).
colon cancer (1 paper, 2012).
kidney damage (1 paper, 2022). "Variants in TAS2R43 affect the receptor’s responses to aristolochic acid, a carcinogenic contaminant of wheat supplies in Eastern Europe, and predict kidney damage in exposed populations." (PMID 36303543, 2022).
Obesity (1 paper, 2022). Accumulation of substantial excess body fat. "The broadly tuned TAS2R agonist DB decreased DEFA6 mRNA expression in crypts of TAS2R43+ individuals by 43.4% ± 5.9 % (P < 0.001) and to a lesser extent in TAS2R43– individuals with obesity (26.7% ± 8.8%, P < 0.05)." (PMID 34784295, 2022). "Treatment (4 h) of jejunal crypts from TAS2R43+ patients with obesity with the TAS2R43 agonist aloin (30 M, n = 6) versus vehicle (n = 8) resulted in the identification of 10 DEGs." (PMID 34784295, 2022). "Double immunofluorescence staining of primary jejunal crypt cultures from patients with obesity showed that the bitter taste receptor TAS2R43 colocalized with α-defensin 5+ cells, a marker for Paneth cells, and with mucin 2+ cells, a marker for goblet cells." (PMID 34784295, 2022). "A limitation of our findings is that we conducted the TAS2R43+ versus TAS2R43– studies solely in jejunal crypts derived from patients with obesity." (PMID 34784295, 2022). "In samples from TAS2R43+ W patients with obesity (43%, n = 6), aloin-CSN significantly (P < 0.05) increased E. coli growth compared with Krebs-CSN and its bacteriostatic control." (PMID 34784295, 2022). "Of the 187 TAS2R43+ cells (n = 3 patients with obesity) analyzed, 42 cells stained positive for α-defensin 5 (22 %)." (PMID 34784295, 2022). "Paneth cells colocalize with TAS2R43 and TAS2R10+ cells, but goblet cells colocalize only with TAS2R43 in jejunal crypts of individuals with obesity." (PMID 34784295, 2022). "In another set of 108 TAS2R43+ cells (n = 3 patients with obesity), 36 cells colocalized with mucin 2+ cells (33 %)." (PMID 34784295, 2022). "Treatment of crypts from patients with obesity, independent of TAS2R43 genotype, with 1 mM DB resulted in 120 DEGs compared with control-treated (DMEM-treated) crypts, as identified by an adjusted P value (q) of less than 0.05." (PMID 34784295, 2022).
TAS2R43 also shares sentences with these, for which no sentence is quoted: cancer (1 paper); cavernous hemangioma (1); glioblastoma (1); glioma (1); inflammatory bowel disease (1); melanoma (1); tumor (1).